GAS2 (growth arrest specific 2)
Diseases named in the same sentence as GAS2 in open-access papers (continued):
Sharing a sentence is not in itself a finding about the gene and the disease.
cancer (10 papers, 2011 to 2025). A tumor composed of atypical neoplastic, often pleomorphic cells that invade other tissues. "Given the significance of GAS2 as a cytoskeleton-associated protein, it is imperative to explore its potential role in cancer progression through cytoskeletal regulation." (PMID 39744572, 2025). "For GAS2 protein, the mis‐sense mutation of S133L/E134Kfs*17 with the highest frequency was only detected in four cancer cases." (PMID 33103301, 2021). "Additionally, examination of TCGA database data allowed us to characterize the mutation landscape of GAS2 across different cancer types, where mutation rates were generally below 5%." (PMID 39744572, 2025). "We confirmed in an independent cohort that GAS2 is robustly hypomethylated and overexpressed in all the studied cell samples, thus emerging as one of the rare genes in which promoter hypomethylation is associated with expression reactivation in cancer cells." (PMID 29575763, 2018). "Furthermore, we investigated specific mutation frequencies within GAS2 across all cancer cases." (PMID 39744572, 2025). "In general, compared with normal cells, if GAS2 is highly expressed in the tumor cells, it has a cancer-promoting effect, and if GAS2 is low expressed in the tumor cells, it has a cancer-inhibiting effect." (PMID 39744572, 2025). "The heterogeneity of cancer necessitates a nuanced investigation into how GAS2 functions within different tumor microenvironments and molecular contexts." (PMID 39744572, 2025). "Analysis of the GEPIA2 database revealed distinct expression patterns of GAS2 and Calpain-2 among various cancer patients." (PMID 39744572, 2025). "While recent years have seen significant progress in unraveling the functions of GAS2, there remains a notable gap in our understanding of its roles across various cancer types." (PMID 39744572, 2025). "This review aims to elucidate the structural and functional aspects of GAS2, with a particular emphasis on its implications in cancer." (PMID 39744572, 2025). "In this review, we aim to summarize recent research on the detailed structural characteristics and biological functions of GAS2 signaling, with a particular focus on its roles in different types of cancers." (PMID 39744572, 2025). "GAS2 (growth arrest specific 2) is involved in an array of biological processes, including cytoskeletal reorganization, the cell cycle, apoptosis, cancer development, and the promotion of senescence." (PMID 38674024, 2024). "Previous studies have suggested that targeting GAS2 against cancer cells is due to the degradation of beta-catenin and the reduction of its transcriptional activity." (PMID 24465953, 2014). "In light of this, a better understanding of the role of Gas2 functions in cell division and how Gas2 is regulated will aid the development of improved cancer therapies." (PMID 21931817, 2011). "GAS2 has a dual function in cancer cell growth: on the one hand, it enhances the sensitivity of cancer cells to chemoradiotherapy and prevents malignant transformation of normal cells; but on the other hand, it maintains the growth of cancer cells." (PMID 39744572, 2025). "Therefore, further research efforts aimed at elucidating the multifaceted roles of GAS2 in different cancer types and uncovering alternative regulatory mechanisms are essential for advancing our comprehension of cancer biology and improving clinical outcomes." (PMID 39744572, 2025).
cancer (continued). "Targeting the GAS2-Calpain axis using these peptides could activate Calpain-2, thereby reducing abnormal protein accumulation and presenting a novel avenue for cancer therapy." (PMID 39744572, 2025). "Thus, a comprehensive understanding of GAS2's role in different cancer types is crucial for developing targeted antineoplastic therapies." (PMID 39744572, 2025). "Consequently, targeting GAS2 signaling for cancer therapy remains in the preclinical stage, necessitating a detailed understanding of its roles across different cancer types." (PMID 39744572, 2025). "GAS2 promotes tumor progression through different mechanisms in different cancers." (PMID 39744572, 2025). "Accumulating evidence has shown that the GAS2/Calpain2 axis plays a dual role in cancer cells." (PMID 36054080, 2022). "GAS2 plays a dual role in cancer cells; however, most studies have not provided in vivo evidence." (PMID 36054080, 2022). "Several studies have provided evidence suggesting that Gas2 activity is mis-regulated in cancer." (PMID 21931817, 2011). "Human gas2 is located on the short arm of Chromosome 11 and genetic rearrangements or deletions of this region are frequently found in tumors and sporadic human cancers." (PMID 21931817, 2011). "In addition, the roles of GAS2 in cancer development, progression, metastasis and relapse might be not the same." (PMID 39744572, 2025). "Additionally, while the interaction between GAS2 and Calpain-2 has been well-documented, it is imperative to explore potential alternative mechanisms through which GAS2 may exert its effects on cancer occurrence and progression." (PMID 39744572, 2025). "Thus GAS2 has dual function in human cancers depending on what substrate calpain degrades." (PMID 24465953, 2014). "Other genes down-regulated by rosiglitazone belonged mainly to two functional groups: “cancer” (RPS27A, SORBS2, STIP1, FGA, FGFR2, SSH3, EPN1) and cell death (SORBS2, STIP1, GAS2, EPN1)." (PMID 22761953, 2012). "AP2α was indeed found to interact with the predicted sites on the GAS2 and on KLK-5 upstream regulatory sequences in the cancer cells as well as to the AP2α binding site in the promoter of the estrogene receptor gene used as a positive control (ESR1)." (PMID 21876733, 2011).
tumor (7 papers, 2012 to 2025). "The functional outcome of GAS2 is highly dependent on the specific substrates of Calpain-2 and cellular environment, particularly within tumor cells." (PMID 39744572, 2025). "Collectively, these findings underscore the multifaceted role of GAS2 in tumor suppression, either by inhibiting tumor cell proliferation or sensitizing tumor cells to chemotherapy drugs." (PMID 39744572, 2025). "The results implied that the tumor apoptosis was induced by the upregulated expression of HtrA2, caspase 6, caspase 7, caspase 10, Gas2, and Lamin A." (PMID 27275821, 2016). "It is yet to be understood whether the GAS2 protein displays different cytoskeletal regulatory mechanisms in solid and non‐solid tumour cells, which is responsible for the dual anti‐tumour and tumour‐promoting role." (PMID 33103301, 2021). "Further, GAS2 can facilitate the tumour formation of THP‐1 cells in nude mice." (PMID 33103301, 2021). "In addition, the member genes FGF19, GAS2, BMP7, TNFSF11, and FGFR3 are all known to play important roles in tumor genesis and progression." (PMID 22863767, 2012). "Only a few studies are investigating the role of GAS2 in oncogenesis and there is no consensus on whether GAS2 acts as a tumor suppressor or oncogene." (PMID 33333841, 2020).
infection (2 papers, 2019 to 2020). The state of being infected such as from the introduction of a foreign agent such as serum, vaccine, antigenic substance or organism. "In U. maydis, glucosidase I Gls1 is required for the initial stages of infection following appressorium penetration, and glucosidase II β-subunit Gas2 (GTB1) is required for efficient fungal spreading inside infected tissues." (PMID 32092131, 2020).
genetic diseases (1 paper, 2025). "Our biochemical data can explain the genetic diseases caused by GAS2 mutations." (PMID 40169809, 2025).
GAS2 also shares sentences with these, for which no sentence is quoted: hematological disorders (2 papers); prostate carcinoma (2); Alzheimer disease (1); autosomal dominant nonsyndromic hearing impairment (1); colon cancer (1); essential thrombocythemia (1); Hearing impairment (1); idiopathic myelofibrosis (1); malignant glioma (1); meningioma (1); myeloid leukemia (1); ovarian carcinoma (1); pancreatic cancer (1); Parkinson disease (1); polycythemia vera (1); septicaemia (1).